CTSZ (cathepsin Z)
Description:
Exhibits carboxy-monopeptidase as well as carboxy-dipeptidase activity. Capable of producing kinin potentiating peptides (By similarity).
Synonyms: CTSX
Tractability: Small molecule: a high-quality ligand is known; it belongs to a druggable protein family. Antibody: its Gene Ontology location is reachable by antibodies, with high confidence; UniProt predicts a signal peptide or a membrane-spanning region. PROTAC: ubiquitination databases record sites on it; its protein half-life has been measured; a small molecule that binds it is known.
Target class: Cysteine protease; Cysteine protease CA clan; Enzyme; Protease; Cysteine protease C1A family
Gene: Protein-coding gene on chromosome 20 (58,985,686 to 59,008,238, reverse strand). Ensembl gene ENSG00000101160.
Subcellular location: Lysosome
Subcellular location (Human Protein Atlas): Vesicles
Pathways (Reactome):
Vesicle-mediated transport: COPII-mediated vesicle transport; Cargo concentration in the ER; Lysosome Vesicle Biogenesis
Immune System: Neutrophil degranulation
Metabolism of proteins: Metabolism of Angiotensinogen to Angiotensins
Gene Ontology:
Molecular function: carboxypeptidase activity; cysteine-type carboxypeptidase activity; cysteine-type peptidase activity; protein binding
Biological process: negative regulation of plasminogen activation; proteolysis; angiotensin maturation; epithelial tube branching involved in lung morphogenesis
Cellular component: cell cortex; cytoplasmic vesicle; endoplasmic reticulum; extracellular exosome; extracellular matrix; extracellular region; lysosome; COPII-coated ER to Golgi transport vesicle; endoplasmic reticulum lumen; endoplasmic reticulum-Golgi intermediate compartment membrane; ficolin-1-rich granule lumen; plasma membrane; specific granule lumen; cell surface; growth cone
Genetic constraint (gnomAD): Loss-of-function variants: 47 observed, 36.79 expected, observed/expected ratio (o/e) 1.28, 90% interval 1.01 to 1.63. The upper end of that interval is the gene's LOEUF score, 1.63, which puts it in group 6 of 6, group 1 being the genes least tolerant of losing a copy. Missense variants: 397 observed, 403.41 expected, observed/expected ratio (o/e) 0.98, 90% interval 0.91 to 1.07. Synonymous variants: 168 observed, 158.29 expected, observed/expected ratio (o/e) 1.06, 90% interval 0.94 to 1.21.
Homologues: Orthologues: chimpanzee CTSZ (100% identical), macaque CTSZ (95% identical), pig CTSZ (84% identical), rat Ctsz (84% identical), guinea pig CTSZ (83% identical), mouse Ctsz (83% identical), dog CTSZ (82% identical), rabbit CTSZ (81% identical), tropical clawed frog ctsz (67% identical), zebrafish ctsz (64% identical), Caenorhabditis elegans cpz-2 (46% identical). Paralogues in human: CTSC (29% identical), TINAGL1 (29% identical), CTSV (27% identical), TINAG (27% identical), CTSH (26% identical), CTSB (26% identical), CTSL (25% identical), CTSS (24% identical), CTSK (24% identical), CTSO (23% identical), CTSF (22% identical), CTSW (20% identical).
Diseases named in the same sentence as CTSZ in open-access papers:
CTSZ is named in the same sentence as 88 diseases in open-access papers, as found by Europe PMC text mining. Sharing a sentence is not in itself a finding about the gene and the disease. The quoted sentences say what the papers report.
breast carcinoma (9 papers, 2006 to 2025). "Analysis of peripheral blood samples from breast cancer patients revealed that the methylation level of cathepsin Z DNA is associated with the incidence of breast cancer, especially early-stage breast cancer." (PMID 39944834, 2025). "Specifically, we discovered that hypomethylation of the CTSZ gene is associated with early-stage breast cancer in premenopausal Chinese women." (PMID 37274256, 2023). "Case-control studies have shown that changes in CTSZ methylation levels in peripheral blood may be associated with breast cancer, particularly in young women, and have the potential to be a potential biomarker for early breast cancer." (PMID 40129966, 2025). "Overall, our findings suggest that altered CTSZ methylation levels in peripheral blood may be associated with breast cancer, particularly in young women, and may serve as a potential biomarker for early-stage BC." (PMID 37274256, 2023). "We found that ANXA2R protects against in situ breast cancer by reducing the expression of cathepsin F. PRX and CRY2 are protective factors for both cathepsin Z and in situ breast cancer." (PMID 39944834, 2025). "To provide evidence for the selection of early markers for breast cancer, we explored the methylation levels between the CTSZ gene and breast cancer among Chinese women through a case-control design in this study." (PMID 37274256, 2023). "Cathepsin Z (CTSZ) is a cysteine protease that has been little-studied in breast cancer, but its overexpression in hepatocellular carcinoma increased the EMT and the expression of proteins involved in matrix remodeling." (PMID 36768435, 2023). "An additional protein family of interest is the CTS proteins; in the present study, five CTS proteins (CTSB, CTSC, CTSD, CTSH and CTSZ) were identified to be upregulated in breast cancer." (PMID 24932247, 2014). "Sevennich and colleagues proved that combined inhibition of Cathepsin B and Cathepsin Z inhibited breast cancer metastasis in mice." (PMID 21966391, 2011). "The methylation of cathepsin Z DNA holds promise as a biomarker for early-stage breast cancer." (PMID 39944834, 2025). "Thus, we hypothesized that methylation level on the site of CTSZ may effect breast cancer." (PMID 37274256, 2023). "These screens were complemented by proteome analysis of tumor interstitial fluid (TIF) derived from MMTV-PyMT primary breast cancers with graded CTSB and CTSZ expression levels." (PMID 32385587, 2021). "So far, there have been no studies about the correlation between CTSZ methylation and breast cancer." (PMID 37274256, 2023). "Therefore, we performed a quantitative secretome comparison using differential isotope labeling of the cell-conditioned medium (CCM) of co-cultures comprising PyMT breast cancer cells and Mɸ either wild type or double knock-out for CTSB and CTSZ (Mɸ Ctsb−/−; Ctsz−/−)." (PMID 32385587, 2021). "Similarly, high expression of the cathepsin family of proteases (CTSC, CTSZ, CTSB) was found to be indicative of poor prognosis in breast cancer patients but appeared to have no significant predictive value in prostate cancer patients." (PMID 17183660, 2006).
prostate carcinoma (7 papers, 2006 to 2025). A carcinoma that arises from epithelial cells of the prostate gland. "Here, we analyzed CTSZ expression in healthy and tumor tissues and evaluated the diagnostic and prognostic implications of CTSZ mRNA expressed by blood cells in prostate cancer." (PMID 34378678, 2021). "Previous studies showed that CTSZ is involved in the development of neurodegenerative disorders, Huntington’s disease and other polyglutamine diseases, multiple sclerosis, and gastric and prostate cancer; furthermore, variants in this gene are associated with susceptibility to tuberculosis." (PMID 29795304, 2018). "mIF staining further confirmed the spatial co-localization of CTSZ with both PD-1 and PD-L1 in prostate cancer tissues (P< 0.05), reinforcing their functional association within the tumor microenvironment." (PMID 40568593, 2025). "The exosomal (CD9- CD81-SCARB2) (average enrichment 2.40) and lysosomal (CTSD- LAMP2- CTSZ- SPNS1- PSAP) (average enrichment 4.15) proteins were also enriched in exosomes from prostate cancer patients." (PMID 26196085, 2015). "CTSZ has also been explored for prognostic value and roles in tumor progression across many cancers, including breast, colorectal, gastric, and prostate cancers, and hepatocellular carcinoma." (PMID 40924769, 2025). "The aminopeptidase CTSH has been shown to clip talin, thereby regulating prostate cancer cell motility, and the carboxypeptidase CTSZ (also known as CTSX) regulates T cell morphology by cleaving the β2 integrin LFA‐1." (PMID 35203107, 2022).
hepatocellular carcinoma (6 papers, 2011 to 2025). A malignant tumor that arises from hepatocytes. "Previous reports have revealed a correlation between high CTSZ expression levels and advanced malignancy in hepatocellular carcinomas and colorectal, gastric, and prostate cancer." (PMID 38184627, 2024). "The aim of this study was to characterize the oncogenic function and mechanism of Cathepsin Z (CTSZ) at 20q13.3, a frequently amplified region in hepatocellular carcinoma (HCC)." (PMID 21966391, 2011).
Alzheimer disease (5 papers, 2017 to 2025). A progressive, neurodegenerative disease characterized by loss of function and death of nerve cells in several areas of the brain leading to loss of cognitive function such as memory and language. "To date, cathepsin Z has been found to be involved in cancer models, rheumatoid arthritis, Alzheimer’s disease, Sjogren’s syndrome, and primary biliary cholangitis." (PMID 34864055, 2022). "Furthermore, a comprehensive comparative gene expression analysis of mouse models of MS (EAE), Alzheimer’s disease and stroke, found that cathepsin Z is one of eighteen genes whose expression is increased in all three models of neuroinflammation." (PMID 28486971, 2017). "In the brain, Alzheimer’s disease and memory-related genes (Camk2n1, Apod, and Serpina3n), and immune-response-related genes (Spp1, CD68, GFAP, Mpeg, Ddx3y, Lyz2, CTSZ, Tyrobp, C4b, and C1qa), were selected for mRNA qPCR analysis in adenine-induced CKD mice." (PMID 35447931, 2022).
colorectal cancer (5 papers, 2019 to 2025). A primary or metastatic malignant neoplasm that affects the colon or rectum. "Prior studies have shown that elevated CTSZ expression is significantly associated with unfavorable clinical outcomes in multiple malignancies, including renal cell carcinoma, colorectal cancer, and esophageal cancer." (PMID 40568593, 2025). "KMT2A can also interact with p65 and upregulate cathepsin Z, a known regulator of cancer progression in colorectal cancer." (PMID 39303915, 2024). "The histone methyltransferase KMT2A promotes colorectal cancer metastasis via activation of cathepsin Z." (PMID 34924998, 2021). "There is a favourable correlation between the proportion of APOE+CTSZ+CD14+ cells and regulatory T cells in colorectal cancer samples." (PMID 39187937, 2024). "Furthermore, a significant abundance of APOE+CTSZ+CD14+ cells, which exhibit immunosuppressive properties by increasing the expression of anti‐inflammatory genes, has been detected in a substantial number of tumour specimens, specifically in cases of colorectal cancer." (PMID 39187937, 2024).
glioma (5 papers, 2020 to 2026). A benign or malignant brain and spinal cord tumor that arises from glial cells (astrocytes, oligodendrocytes, ependymal cells). "Compared with normal glial cells, the expression of ALDH3B1 and CTSZ is significantly upregulated in glioma cells." (PMID 40129966, 2025). "In solid tissue sites, all healthy tissues expressed less CTSZ than malignant tumors, except low-grade gliomas (P=0.010)." (PMID 34378678, 2021). "Of these, ten genes (CTSZ, EFEMP2, ITGA5, KDELR2, MDK, MICALL2, MAP 2 K3, PLAUR, SERPINE1 and SOCS3) can potentially classify patients with gliomas into different risk groups." (PMID 32878880, 2020). "Although there is limited research on the role of CTSZ in gliomas, studies in pancreatic neuroendocrine tumors have shown that intracellular CTSZ in tumor cells can promote proliferation, while both intracellular CTSZ in tumor cells and CTSZ secreted by TAMs can promote tumor invasion." (PMID 39458936, 2024). "CTSZ may have similar functions in gliomas and the microenvironment." (PMID 39458936, 2024). "Further exploration of the GEPIA database revealed that CD47, CTSZ, and SLC11A1 were highly expressed in various cancers, such as glioma, acute myeloid leukemia-like tumors, and pancreatic cancer." (PMID 40129966, 2025).
multiple sclerosis (5 papers, 2017 to 2025). A progressive autoimmune disorder affecting the central nervous system resulting in demyelination. "Loss of CtsX limits Th17 responses and neuroinflammation in the experimental autoimmune encephalomyelitis (EAE) mouse model of multiple sclerosis, and both CtsZ and CtsX are implicated in inflammation across cancer, silicosis, trauma, and chronic infections." (PMID 41369389, 2025). "Hypomethylation of the cathepsin Z locus has been proposed as an epigenetic risk factor for multiple sclerosis (MS)." (PMID 28486971, 2017). "In a model of multiple sclerosis—experimental autoimmune encephalomyelitis (EAE)—mice deficient in cathepsin Z consistently developed lower levels of neuroinflammation and displayed disproportionally lower levels of circulating IL-1β." (PMID 28486971, 2017). "Furthermore, mouse and human studies have investigated CTSZ for roles in aging and in a number of endogenous conditions, including multiple sclerosis, primary biliary cholangitis, osteoporosis, and Alzheimer’s." (PMID 40924769, 2025). "In mice with multiple sclerosis, a lack of CTSZ can significantly reduce the level of IL-1β in the serum and reduce neuroinflammation." (PMID 36370154, 2023).
pancreatic neuroendocrine tumor (5 papers, 2019 to 2025). Pancreatic endocrine tumor, also known as pancreatic neuroendocrine tumor (PNET), describes a group of endocrine tumors originating in the pancreas that are usually indolent and benign, but may have the potential to be malignant. "Cathepsin Z (CtsZ) is a protease provided by both cancer cells and macrophages in human and mouse pancreatic neuroendocrine tumors." (PMID 40129966, 2025). "CTSZ promotes pancreatic neuroendocrine tumor growth and progression from both cancer cell-derived and tumor-associated macrophage-derived sources." (PMID 35494076, 2022). "Similarly, cathepsin Z was shown to protect tumor cells from chemotherapy in pancreatic neuroendocrine tumor xenografts." (PMID 33276524, 2020).
primary biliary cholangitis (5 papers, 2018 to 2025). Primary biliary cholangitis (PBC) is a chronic and slowly progressive cholestatic liver disease of autoimmune etiology characterized by injury of the intrahepatic bile ducts that may eventually lead to liver failure. "Our recent genome-wide association study found that the NELFCD/CTSZ locus was significantly associated with progression of primary biliary cholangitis (PBC) to jaundice stage in the Japanese population." (PMID 30087368, 2018). "CTSZ has been shown to be markedly increased in hepatocytes from patients with later stages of cholestatic liver disease, particularly primary biliary cholangitis." (PMID 34440927, 2021). "In this study, we report several novel findings about the role of cathepsin Z in the pathogenesis of cholestatic liver diseases, particularly primary biliary cholangitis." (PMID 30087368, 2018).
tuberculosis (4 papers, 2019 to 2025). A chronic, recurrent infection caused by the bacterium Mycobacterium tuberculosis. "Most importantly, independent studies have associated single nucleotide polymorphisms in Cathepsin Z with increased susceptibility to tuberculosis." (PMID 31117286, 2019). "Finally, we identified, as a possible candidate gene, the CTSZ gene (located within selection signals on chromosome 13), which was associated with tuberculosis (Mycobacterium tuberculosis) susceptibility in humans." (PMID 35627251, 2022).
COVID-19 (3 papers, 2021 to 2023). A disease caused by infection with severe acute respiratory syndrome coronavirus 2. "Indeed, most recent proteomic analysis of COVID-19 autopsies suggested an overall upregulation of the cathepsin family members, including CTSB, CTSD, CTSE, CTSH, CTSK, CTSS, and CTSZ, in the lung of the COVID-19 patients." (PMID 34335974, 2021). "Recent human COVID-19 autopsy and transplant lung studies identified abundant interstitial pro-fibrotic monocyte-derived macrophages characterized by increased expression of SPP1, MMP9, and CTSZ." (PMID 35857635, 2022).
gastric cancer (3 papers, 2014 to 2024). A primary or metastatic malignant neoplasm involving the stomach. "Cathepsin Z is expressed in prostate and gastric carcinoma as well as in macrophages of gastric mucosa, especially after infection with Helicobacter pylori infection, but also in glial cells." (PMID 35008858, 2021).
Jaundice (3 papers, 2018 to 2026). Yellow pigmentation of the skin due to bilirubin, which in turn is the result of increased bilirubin concentration in the bloodstream. "For instance, prior research has implicated the cathepsin Z (CTSZ) locus in jaundice progression and highlighted significant correlations between UGT1A gene variants and jaundice susceptibility." (PMID 41544045, 2026). "The SNP rs13720 (odds ratio [OR] = 2.15, 95% confidence interval [CI] = 1.58–2.94, P = 7.62 × 10−7), which is located in the 3′UTR of cathepsin Z (CTSZ), showed the strongest association with progression to jaundice stage in PBC." (PMID 29795304, 2018). "Using this method of classification, we recently found that genetic polymorphisms (rs13720 and rs163800) at the NELFCD/CTSZ locus were associated with progression to jaundice stage in PBC in a Japanese population." (PMID 30087368, 2018). "SNP rs13720, which is located in the 3′UTR of cathepsin Z (CTSZ), showed the strongest association (odds ratio [OR] = 2.15, P = 7.62 × 10−7) with progression to jaundice stage in GWAS." (PMID 29795304, 2018). "In conclusion, our GWAS identified NELFCD and CTSZ as novel loci associated with progression to jaundice stage in PBC." (PMID 29795304, 2018). "In this study, we demonstrated that CTSZ variants are associated with progression to jaundice stage in PBC, mediated through a reduction in CTSZ mRNA levels." (PMID 29795304, 2018). "Therefore, we postulate that the risk allele of CTSZ might influence the regulation of cellular and/or immune functions through altered cleavage of various molecules, including self and exogenous proteins, leading to progression to jaundice stage in PBC." (PMID 29795304, 2018). "GWAS and subsequent validation studies using a total of 1,375 samples (173 jaundice-stage and 1,202 early-stage Japanese PBC patients) identified a strong association between rs13720, located the NELFCD/CTSZ locus, and progression to jaundice-stage in PBC." (PMID 29795304, 2018). "The risk allele of rs163800 for jaundice-stage progression was associated with elevated NELFCD and reduced CTSZ mRNA levels in both tissue types." (PMID 29795304, 2018). "In this analysis, an intronic SNP of CTSZ, rs163800, but not rs13720, exhibited the most significant association with progression to jaundice stage (OR = 2.16, 95% CI = 1.62–2.87, P = 8.57 × 10−8)." (PMID 29795304, 2018). "We measured serum cathepsin Z levels in three clinical stages of PBC (early-stage n = 25, late-stage n = 17, jaundice-stage n = 29), in two clinical stages of CHC (early-stage n = 10, late-stage n = 10), and in obstructive jaundice (n = 12)." (PMID 30087368, 2018). "Interestingly, the intensity of cathepsin Z staining in hepatocytes increased with progression of PBC, which was also shown by immunohistochemical scoring (jaundice-stage v.s early-stage, P = 4.9 × 10−5, jaundice-stage v.s late-stage, P = 4.7 × 10−3)." (PMID 30087368, 2018). "Functional SNPs at these loci may be involved in progression to jaundice stage via alteration of both NELFCD and CTSZ mRNA levels." (PMID 29795304, 2018). "Serum cathepsin Z levels in obstructive jaundice (n = 12, 1.78 ± 1.15 ng/ml) were significantly higher compared to those of CHC (P = 0.02), but significantly lower than those of jaundice-stage PBC (P = 0.002)." (PMID 30087368, 2018). "However, in the current study, MRP2 was mainly localized in the cytoplasm of hepatocytes in jaundice-stage PBC and serum cathepsin Z levels did not decrease after UDCA treatment, indicating that UDCA is not effective at restoring hepatocyte polarity and excretion of cathepsin Z." (PMID 30087368, 2018).